ZNF322 (zinc finger protein 322)
Description:
Transcriptional activator. Important for maintenance of pluripotency in embryonic stem cells (By similarity). Binds directly to the POU5F1 distal enhancer and the NANOG proximal promoter, and enhances expression of both genes (By similarity). Can also bind to numerous other gene promoters and regulates expression of many other pluripotency factors, either directly or indirectly (By similarity). Promotes inhibition of MAPK signaling during embryonic stem cell differentiation (By similarity).
Synonyms: ZNF322A; ZNF388; ZNF489; bA457M11.3; bA457M11.2; HCG12
Tractability: PROTAC: ubiquitination databases record sites on it.
Gene: Protein-coding gene on chromosome 6 (26,634,383 to 26,659,759, reverse strand). Ensembl gene ENSG00000181315.
Subcellular location: Cytoplasm; Nucleus
Subcellular location (Human Protein Atlas): Nucleoplasm; Centrosome; Cytosol
Gene Ontology:
Molecular function: DNA-binding transcription factor activity, RNA polymerase II-specific; RNA polymerase II cis-regulatory region sequence-specific DNA binding; cis-regulatory region sequence-specific DNA binding; DNA-binding transcription factor activity
Biological process: regulation of transcription by RNA polymerase II; positive regulation of stem cell population maintenance; regulation of DNA-templated transcription
Cellular component: cytoplasm; cytosol; nucleoplasm; nucleus
Genetic constraint (gnomAD): Loss-of-function variants: 1 observed, 11.15 expected, observed/expected ratio (o/e) 0.0897, 90% interval 0.031 to 0.43. The synonymous counts are far from expectation, so gnomAD's model fits this gene poorly and the ratio says little. Missense variants: 32 observed, 188.45 expected, observed/expected ratio (o/e) 0.17, 90% interval 0.13 to 0.23. Synonymous variants: 17 observed, 56.85 expected, observed/expected ratio (o/e) 0.3, 90% interval 0.2 to 0.45.
Homologues: Orthologues: chimpanzee ZNF322 (99% identical), macaque ZNF322 (98% identical), pig ZNF322 (95% identical), dog ZNF322 (94% identical), rabbit ZNF322 (92% identical), rat Zfp322a (90% identical), mouse Zfp322a (85% identical), guinea pig ZNF322 (69% identical). Paralogues in human: ZNF229 (47% identical), ZNF227 (47% identical), ZNF235 (47% identical), ZNF33B (47% identical), ZNF484 (47% identical), ZNF605 (47% identical), ZNF182 (46% identical), ZNF585B (46% identical), ZNF708 (46% identical), ZNF841 (46% identical), ZNF726 (46% identical), ZNF836 (46% identical), and 164 more.
Diseases named in the same sentence as ZNF322 in open-access papers:
ZNF322 is named in the same sentence as 13 diseases in open-access papers, as found by Europe PMC text mining. Sharing a sentence is not in itself a finding about the gene and the disease. The quoted sentences say what the papers report.
lung carcinoma (15 papers, 2012 to 2025). "Similarly, AKT serine/threonine kinase (AKT) facilitates zinc finger protein 322 (ZNF322) phosphorylation to improve its stability in lung cancer." (PMID 38439082, 2024).
gastric cancer (2 papers, 2018 to 2022). A primary or metastatic malignant neoplasm involving the stomach. "Intriguingly, a recent study suggested that miR-4317 could repress the proliferation of gastric cancer cells by targeting and suppressing ZNF322." (PMID 30227870, 2018).
tumor (7 papers, 2012 to 2024). "Divergent effects were observed for tumor Gleason score, with two genes being associated with a higher Gleason score (ITGAX; OR = 3.87 [1.88–7.56] and ZNF322; OR = 2.26 [1.27–4.02]) and two genes with a Gleason score <7 (CCL19; OR = 0.46 [0.24–0.88] and HIST1H1A; (OR = 0.45 [0.24–0.86])." (PMID 25411967, 2014).
ZNF322 also shares sentences with these, for which no sentence is quoted: cancer (4 papers); adenocarcinoma (1); colorectal cancer (1); duodenitis (1); gastritis (1); infection (1); lung adenocarcinoma (1); lung squamous cell carcinoma (1); prostate carcinoma (1); squamous cell carcinoma (1).